EGFR (epidermal growth factor receptor)
Diseases named in the same sentence as EGFR in open-access papers (continued):
Sharing a sentence is not in itself a finding about the gene and the disease.
lung cancer (continued). "Further functional characterization studies of AURKA report that AURKA suppression enhances the radiosensitivity of lung cancer and its response to EGFR inhibitors." (PMID 35520289, 2022). "Based on our integrated cohort and the TCGA LUAD cohort, we identified 28774 high-confidence alternative splicing events (ASEs), which affected 8726 genes, including targets for tyrosine kinase inhibitors used to treat lung cancer, such as EGFR, RET, and MET." (PMID 35989380, 2022). "NSCLC cells express EGFR and its derivatives, which play a key role in the pathogenesis of lung cancer, and therefore, the cell blockade of the EGFR signaling represents a promising cancer treatment strategy." (PMID 35740495, 2022). "Hepatocyte growth factor (HGF) is the ligand of the proto-oncogene c-Met; it can trigger MET activation through EGFR bypass signaling and induce lung cancer resistance to EGFR-TKIs." (PMID 35840984, 2022). "CtDNA from 458 primary lung cancer patients was analyzed using a panel of multiplex ddPCRs for EGFR (Ex19Del, G719S, L858R, L861Q and S768I), KRAS G12/G13 and BRAF V600 mutations." (PMID 36413862, 2022). "EGFR is overexpressed on lung cancer, breast cancer, colorectal cancer, ovarian cancer, and other malignant cells." (PMID 35156493, 2022). "More specifically, a nationwide population-based study revealed statins had the potential to amplify the treatment response of lung cancer patients receiving EGFR-TKI therapy." (PMID 35681743, 2022). "After developing acquired resistance to EGFR-TKIs, EGFR-mutant lung cancer cells display higher sensitivity to ferroptosis inducers." (PMID 35151318, 2022). "Knockout of these essential genes significantly decreased tumorigenic properties of EGFR-mutant lung cancer cells." (PMID 35372044, 2022). "Treatment with histone deacetylase (HDAC) inhibitors in combination with EGFR-TKI indeed strongly impedes the establishment of lung cancer DTPs." (PMID 35681591, 2022). "Some diseases have been distinguished using blood-based biomarkers, such as human epidermal growth factor receptor 2 (HER2) for breast cancer and epidermal growth factor receptor (EGFR) for lung cancer." (PMID 35187013, 2022). "The prognostic impact of the miR-1262 rs12740674 variation has been investigated in advanced lung cancer patients treated by EGFR-TKIs." (PMID 35264191, 2022). "Clinical impact of RBM10 downregulation in advanced-stage EGFR-mutant lung cancer treated with an EGFR TKI." (PMID 35579943, 2022). "The EGFR is also a main therapeutic target in lung cancer, since it is frequently overexpressed, exhibits amended signaling or is mutated in non-small cell lung cancer (NSCLC)." (PMID 35216384, 2022). "For example, in the anti-EGFR target therapy using gefitinib for lung cancer, MET (receptor of HGF) amplification leads to resistance by activating ERBB3 signaling." (PMID 35625759, 2022). "Blockade of AhR efficiently improved the outcome of EGFR TKIs, which provides a novel strategy for clinical lung cancer treatment." (PMID 35831824, 2022). "A study has shown that the combined inhibition of Aurora B kinase and EGFR prevents and eliminates the resistance to EGFR inhibitors in lung cancer by promoting BIM and PUMA-mediated apoptosis." (PMID 36233210, 2022). "Osimertinib was found to have a marked therapeutic effect in the FLAURA trial compared with first-generation EGFR TKIs as a first-line treatment for EGFR-mutant lung cancer." (PMID 36082280, 2022). "The addition of anti-angiogenesis drugs to epidermal growth factor receptor (EGFR)–tyrosine kinase inhibitor (TKI) or chemotherapy in patients with EGFR-mutant non–small cell lung cancer (NSCLC) can improve disease control." (PMID 35599308, 2022). "The assumption is that genes most relevant to the EGFR TKI resistance phenotype should be close to either lung cancer or EGFR gene nodes." (PMID 35351890, 2022).
lung cancer (continued). "Although they rarely occur in lung cancer, KRAS mutations combined with EGFR mutations or ALK rearrangement predict poorer response to tyrosine kinase inhibitors (TKIs)." (PMID 36077640, 2022). "For example, targeted antibody therapies for lung cancer with mutant EGFR oncogenes include necitumumab (Portrazza, Eli Lilly and Co.), cetuximab (Erbitux, Eli Lilly and Co.)and amivantamab-vmjw (Rybrevant, Janssen Biotech)." (PMID 35521553, 2022). "Loss of SUV420H2 facilitates upregulation of LINC01510, which promotes the transcription of the oncogene MET and EGFR inhibitor resistance in lung cancer." (PMID 36185333, 2022). "It has been reported that insulin-like growth factor 1 (IGF-1), the ligand of the IGF-1 receptor (IGF-1R), is highly expressed in the TME of the liver metastasis, and the signaling from IGF-1R promotes the tolerance to osimertinib in EGFR-positive lung cancer." (PMID 36140210, 2022). "Targeted therapy with EGFR inhibitors has shown a significant therapeutic effect in patients with EGFR-mutant lung cancer." (PMID 36438567, 2022). "Because HER2 activation mediates resistance to targeted drugs in EGFR-mutated lung cancer, the study assessed its functional relevance in KRAS G12C-positive lung cancer." (PMID 36338994, 2022). "It is the earliest gene to be uncovered, and EGFR-TKIs were adopted for clinical work, which markedly changed the therapy strategy and yielded better therapeutic prospects in lung cancer, particularly in adenocarcinoma." (PMID 35814445, 2022). "Approximately 80% of patients with EGFR‐mutant lung cancer respond to EGFR- TKIs therapy at initial treatment." (PMID 36119545, 2022). "EGFR has been found in 40%–80% of patients with non-small cell lung cancer and both premalignant and malignant lung tumors." (PMID 36713381, 2022). "Overexpression of EGFR is frequently found in lung cancer, especially in NSCLCs, with previous studies demonstrating a correlation between high EGFR expression and a poor prognosis in NSCLC patients." (PMID 35235599, 2022). "Based on these clinical examples, we next undertook a study of all putative fusion oncogenes in EGFR mutant lung cancer via a comprehensive analysis of 3637 patients with lung cancer." (PMID 36153311, 2022). "Use of an EGFR-TKI alone for BM in EGFR-mutant lung cancer patients showed outcomes comparable to those who received upfront RT followed by EGFR-TKI therapy." (PMID 35069906, 2022). "We, therefore, went further to test the ability of Carfilzomib to shrink tumors in our transgenic mouse models of autochthonous lung cancer driven by drug‐resistant EGFR mutant." (PMID 34898004, 2022). "The epidermal growth factor receptor (EGFR) tyrosine kinase inhibitor (TKI) erlotinib has been proven to be effective in patients with advanced stage lung cancer." (PMID 35360423, 2022). "To confirm the critical role of EGFR in TRAF4‐mediated proliferation of lung cancer cells, we deleted the Egfr gene in the TRAF4 inducible A549 cell line." (PMID 35748027, 2022). "EGFR-TKIs (such as gefitinib) significantly increase the overall survival of lung cancer patients with EGFR mutants." (PMID 35163707, 2022). "Although EGFR-targeting agents are currently approved for nonsmall cell lung cancer (NSCLC) on the basis of their effectiveness, the response is limited to patients with gain-of-function mutations of EGFR such as exon 19 deletion and L858R mutation." (PMID 35572726, 2022). "Several mechanisms of resistance have been described to anti-EGFR-TKI in lung cancer and anti-EGFR monoclonal antibody in colorectal cancer." (PMID 35402275, 2022). "The aims of this study were to improve our understanding on the impact of EGFR inhibition on the immune response in EGFR-driven lung cancer and, furthermore, to gain insights into the impact of combining targeted therapy with immunotherapy on the TME." (PMID 36010935, 2022).
lung cancer (continued). "In summary, the present study demonstrates for the first time that glutamine blockade with JHU083 significantly enhances the efficacy of EVax in controlling the development and growth of EGFR‐driven lung cancer." (PMID 35861366, 2022). "One recent study reported the effect of postoperative EGFR-TKI treatment on residual GGO lesions after lung cancer resection." (PMID 36046337, 2022). "In a similar manner, ncRNAs such as miR-223, lncRNA GAS5 and hsa_circ_0005576 regulate IGF1R expression and subsequently influence the resistance of lung cancer cells to EGFR TKIs." (PMID 36139582, 2022). "We used a large panel of lung cancer cell lines to compare the efficiency of second-generation irreversible EGFR inhibitors afatinib and allitinib to determine the half-maximal inhibitory concentrations (IC50) values." (PMID 35887120, 2022). "It is favorable to overcome the resistance of lung cancer cells to first-, second- and third-generation EGFR-TKIs." (PMID 35847022, 2022). "EGFR mutant lung cancer is the most relevant subset of lung cancer with regards to the biology of steroid hormone signaling and interaction with lung cancer specific therapy." (PMID 35804979, 2022). "Butein also suppresses the protein tyrosine kinase activity of EGFR in HepG2 cells and circumvents gefitinib-resistant lung cancer growth by inhibiting EGFR." (PMID 35745583, 2022). "Lung cancer cells A549 exhibited EGFR reduction when treated with the combination therapy, compared with TKI-afatinib alone, with a reduction of 15.7% (p = 0.0433)." (PMID 35337178, 2022). "Lung cancer cells H1975 showed an EGFR protein reduction of 14% when treated with the combination therapy compared with afatinib alone (p = 0.0120)." (PMID 35337178, 2022). "NIR-PIT and panitumumab (antibody targeting EGFR)-IR700 conjugated inhibited tumor growth in a transgenic mouse model of spontaneous lung cancer, which expressed human EGFR." (PMID 35453596, 2022). "This is in agreement with previous studies that highlighted the synergistic antitumor activity of sorafenib combinations with EGFR inhibitors in various tumors including human non–small cell lung cancer, colorectal cancer, and HCC53,68." (PMID 36284117, 2022). "Similar observations have also been made for EGFR+ lung cancer, which shows a shorter survival in case of squamous compared to adenocarcinoma histology." (PMID 36207130, 2022). "The most frequently found driver mutations in lung cancer are Kirsten rat sarcoma viral (KRAS) oncogene homolog and epidermal growth factor receptor (EGFR) mutations." (PMID 35720364, 2022). "Seven SFK-related genes have been identified as genomic modifiers of EGFR dependence in lung cancer cells harboring mutEGFR26." (PMID 35643725, 2022). "In preclinical studies, anti–PD-1 antibody improved the survival of mice with EGFR-driven lung cancer by enhancing T cell function." (PMID 35132961, 2022). "Mobocertinib, a novel targeted therapy, resulted in clinically meaningful improvement in core lung cancer symptoms and maintained general HRQoL in patients with EGFR ex20ins+ mNSCLC." (PMID 36614913, 2022). "METTL3 promotes tumor development in human lung cancer cells by upregulating the translation of important oncogenes such as EGFR and TAZ." (PMID 36553648, 2022). "The purpose of this study was to detect the molecular evidence of HPV oncoproteins interfering with EGFR nuclear trafficking related to better prognosis in lung cancer." (PMID 36358752, 2022). "Once a lung cancer is dominated by EGFR-mut cells has a very different immune (low immune infiltration) and extra-cellular matrix than a KRAS-mut lung cancer with high immune infiltration and less structured extra-cellular matrix." (PMID 35061724, 2022). "CXCL10 is a cytokine that is elevated during EGFR-TKI treatment in the tumor microenvironment of lung cancer." (PMID 36612121, 2022).
lung cancer (continued). "To further verify the impact of ADAMTS8 on the target therapies of EGFR-mutant lung cancer, we assessed the levels of ADAMTS8 in several LUAD cell lines with mutated EGFR based on the sensitivity of TKI treatment." (PMID 35743687, 2022). "Erlotinib, a subtype of small‐molecule EGFR tyrosine kinase inhibitors (TKIs), has been the first‐line treatment in patients suffering from EGFR‐mutant lung cancer in a number of countries." (PMID 35605028, 2022). "The remainder of lung cancers, the non-small cell lung cancers (NSCLC), express amplifying EGFR (epidermal growth factor receptor) mutations in some 10% and amplifying ALK rearrangements in 4–7%." (PMID 35902427, 2022). "Luteolin treatment also reduced the PM2.5-activated epidermal growth factor receptor (EGFR)-phosphatidylinositol 3-kinase (PI3K)-protein kinase B (AKT) signaling transduction in human H460 lung cancer cells." (PMID 36185331, 2022). "In the context of ncRNAs, however, EMT of EGFR TKI-resistant lung cancer is mainly restricted to the TGFβ pathway, NOTCH pathway and EMT-inducing transcription factors." (PMID 36139582, 2022). "These nanoparticles were coupled with a human anti-EGFR antibody to target the overexpressed hERG1 channel on human lung cancer cell membranes, which increased anticancer efficacy." (PMID 36085575, 2022). "The EGFR SNV described in our corticotroph tumor series was found to be associated with the response to neoadjuvant chemotherapy in patients with breast and lung cancer." (PMID 35563252, 2022). "HER2/HER3 were also found to be upstream transcription factor of CCND1 in lung cancer which is reported to enhance EGFR-TKI resistance." (PMID 35365622, 2022). "To date, there has been no relevant research using EGFR gene drive-positive primary lung cancer cells to screen EGFR-targeted anti-lung cancer drugs in lung organ chips." (PMID 36005014, 2022). "For example, EGFR, EGFR-TKI, EGFR mutation, lung cancer, and erlotinib are important research themes in C1 (NSCLC), which are closely related to the other terms or extended to other themes." (PMID 35072634, 2022). "Lung cancer with complex epidermal growth factor receptor (EGFR) and CTNNB1 comutations is rare, and the efficacy of tyrosine kinase inhibitors (TKIs) is generally poor." (PMID 36519636, 2022). "In our study, we compared the efficacy between first-, second- and third-generation EGFR TKIs for the treatment of mutant-EGFR lung cancer with brain metastasis." (PMID 36612183, 2022). "We demonstrate that a CXCL10/CXCR3 pathway is activated in EGFR-mutant lung cancer cells when cocultured with activated PBMCs and exposed to EGFR-TKI treatment." (PMID 36612121, 2022). "At present, current research is still focused on EGFR-positive lung cancer, but CAR-T-cell treatment of EGFR-mutant NSCLC also needs to be further studied." (PMID 35935943, 2022). "The advanced treatments with EGFR TKIs and ICIs have enabled lung cancer treatment to achieve a step forward." (PMID 35743687, 2022). "In the past decade, the epidermal growth factor receptor (EGFR) has become an important therapeutic target for patients with lung cancer." (PMID 35593080, 2022). "Targeting EGFR has been clinically successful and largely implemented in the treatment of lung cancer." (PMID 35744950, 2022). "The median proportion of signatures 2 and 13 (APOBEC) was higher and signature 24 (Aflatoxin) was lower in baseline group compared with the resistance to EGFR-TKI group in lung cancer." (PMID 35402275, 2022). "Even for patients whose EGFR-mutant lung cancer expressed high PD-L1 (>50%), the response was inferior to EGFR-wildtype high PD-L1 counterparts." (PMID 35884533, 2022). "In lung cancer cell lines, we observed significant correlations between L-scores and cell sensitivity to a number of targeted drugs including EGFR inhibitors." (PMID 35016696, 2022).
lung cancer (continued). "Examples of these paradigms include EGFR inhibitors in EGFR-mutant non–small cell lung cancer (NSCLC) and ALK inhibitors in ALK-translocated NSCLC." (PMID 36506869, 2022). "This study provides insights into the impacts of alterations in the zinc status upon the EGFR activation and expression of EGFR-related proteins in A549 cells, a human lung cancer cell line that serves as a model for NSCLC." (PMID 35216384, 2022). "C-type lectin 11A, which promotes vascular endothelial cell differentiation, is highly expressed in EGFR-mutant lung cancer cells and promotes angiogenesis triggered by VEGF." (PMID 36085020, 2022). "Inhibiting the RAC pathway has been recommended as an alternative option for treating EGFR inhibitor-resistant patients with lung cancer." (PMID 35016696, 2022). "We envision that these types of multiplexed in vivo studies will ultimately contribute to the development of tailored treatments for patients with EGFR mutant lung cancer." (PMID 35252550, 2022). "K-ras-G12C and EGFR-targeted therapeutics against lung cancer appear promising in patients with these mutants and have prolonged survival time in the short term." (PMID 35574342, 2022). "We examined the uptake ability of ND-IgG and ND-Cet in the EGFR-expressed PLC26 lung cancer cells separated from a clinical NSCLC patient." (PMID 36678740, 2022). "Further knocking down these miRNAs enhanced EGFR-TKI-induced apoptosis in EGFR-mutant lung cancer cells." (PMID 35840668, 2022). "Intriguingly, LOC554202 sustains both the Ras/Raf/MEK/ERK and PI3K/AKT/mTOR pathways by activating miR-31, indicating its potential as a promising therapeutic target for EGFR TKI-resistant lung cancer." (PMID 36139582, 2022). "Assiddiq and coworkers used multiple reaction monitoring (MRM) in the H838 lung cancer cell line to study the effect of gefitinib on the phospho-sites of the EGFR protein before and after EGF treatment." (PMID 35563452, 2022). "Some studies have shown that EGFR is significantly correlated with the autophagy activity of lung cancer cells." (PMID 35972910, 2022). "The use of a metastatic model of epidermal growth factor receptor-mutant lung cancer has shown that a pan-RAR antagonist dramatically reduces lung cancer metastasis to the brain." (PMID 35563205, 2022). "Gefitinib (G) is a recommended molecular‐targeted agent for elderly patients with epidermal growth factor receptor (EGFR)‐mutant non‐small cell lung cancer (NSCLC)." (PMID 35562327, 2022). "Several studies explored the efficiency of CT radiomics in predicting survival in advanced lung cancer patients who received EGFR-TKIs and showed promising results." (PMID 35875167, 2022). "The resistance to EGFR-TKIs targeted therapy is currently a major clinical challenge in the treatment of lung cancer." (PMID 35027025, 2022). "-Oncogenic EGFR was shown to silence multiple tumor suppressors in lung cancer cell lines via transcriptional downregulation of TET1 by the C/EBPα transcription factor." (PMID 35269796, 2022). "Aberrant EGFR activation frequently occurs in diverse malignancies, including lung cancer, and triggers a series of tumorigenic events, such as cell proliferation, cell invasion, and metastasis and angiogenesis." (PMID 35408854, 2022). "Knocking down FAS and several components of the NF-κB signaling pathway would explicitly enhance cell death which was induced by erlotinib in EGFR-mutant lung cancer cells." (PMID 36508072, 2022). "hTid-1 has been found to act as an E3-ligase for several interacting proteins such as ErbB2 and EGFR that play important roles in Breast and Lung cancers respectively." (PMID 35854300, 2022). "We then used the same method to verify the relationship between GILncSig and lung cancer driver genes (EGFR and ALK) and obtained similar conclusions." (PMID 35372012, 2022). "The current study focused on the role of stemness factor BMI1 in lung cancer, and its crosstalk with EGFR through JNK‐mediated protein stability regulations." (PMID 35794816, 2022).